LEP (leptin)
Diseases named in the same sentence as LEP in open-access papers (continued):
Sharing a sentence is not in itself a finding about the gene and the disease.
metabolic syndrome (continued). "We assessed the presence of features associated with metabolic syndrome including blood pressure, type II diabetes status (determined by blood levels of A1c), and plasma levels of C-reactive protein (CRP) and leptin." (PMID 38172612, 2024). "Additional studies with mice models using leptin and LDL (low-density lipoprotein) receptor deficiency, stimulating metabolic syndrome, have led to atherosclerosis, dyslipidemia, and obesity." (PMID 38474211, 2024). "Leptin is a hormone produced by white adipocytes, and it is overexpressed in individuals with metabolic syndrome." (PMID 38782951, 2024). "They display hyperphagic behavior when fed a chow or a high-fat diet (HFD) and manifest other aspects of the metabolic syndrome, including leptin and insulin resistance, dyslipidemia, and hyperglycemia." (PMID 38672441, 2024). "Several studies found suggestive linkage evidence on this region for relevant traits including fasting glucose, circulating leptin, T2D, coronary artery disease, and metabolism syndrome." (PMID 38826208, 2024). "The leptin/adiponectin (L/A) ratio was proposed as a predictor of cardiometabolic events due to its identified correlation with metabolic syndrome, IR, and also with carotid intima media thickness." (PMID 39063610, 2024). "Leptin derived from EAT induced myocardial injury in rats with metabolic syndrome independently from the circulating leptin effects." (PMID 38612394, 2024). "The concentrations of early metabolic syndrome biomarkers [adiponectin, leptin, TNF-α, IL-1, IL-6, IL-10, endothelin-1, apolipoprotein B, and lipoprotein (a)] were measured and a cardiopulmonary exercise test (CPET) was performed." (PMID 38254811, 2024). "At a molecular level, BPA can cause dyslipidemia and oxidative stress, release proinflammatory cytokines and adipokines such as TNF-α and leptin, and activate certain transcription factors such as PPAR-y or binding protein 1c." (PMID 39519574, 2024). "The presence of high leptin levels has been proposed as a potential marker for the development of metabolic syndrome." (PMID 37175603, 2023). "Studies in animal models indicate that treatment with doses within the range of human exposure decreases insulin sensitivity and glucose tolerance, induces dyslipidemia, and modifies functional β-cell mass and serum levels of insulin, leptin, and adiponectin." (PMID 37134142, 2023). "In sheep, the multigenerational and intergenerational effects of maternal overnutrition were evaluated over leptin surge and metabolic syndrome, respectively." (PMID 36928446, 2023). "Correlation of leptin and interleukin-1 beta (IL-1β) levels with clinical parameters of metabolic syndrome and osteoarthritis." (PMID 37703108, 2023). "Dyslipidemia, elevated plasma leptin and adiponectin, gallbladder inflammation, and changes in neurometabolites and brain carbohydrate metabolism were also reported." (PMID 38250256, 2023). "These animals exhibited alterations in serum concentrations of other hormones, including leptin and adiponectin, as well as dyslipidemia." (PMID 37134142, 2023). "Females are more protected than males against high-fat diet-induced metabolic syndrome, and sex also influences the production of some adipokines such as leptin and adiponectin." (PMID 37569775, 2023). "As a metabolic syndrome marker, leptin exhibited positive correlation with BMI, WC, WHR and fat mass." (PMID 37853077, 2023). "Insulin resistance, dyslipidemia, and visceral obesity were observed in obese patients with leptin impairment." (PMID 37512517, 2023). "Adiponectin, leptin and resistin belongs to the group of apparent serum markers of metabolic syndrome." (PMID 36826001, 2023). "This leads to the metabolic syndrome and similar to leptin, in vitro studies have shown that ASF produces more IL-6 than VSF making the link between ASF and metabolic syndrome stronger than that for VSF." (PMID 36200436, 2023).
metabolic syndrome (continued). "Consistent with previous reports, the current study showed that HF diet-fed rats developed adiposity, elevated glucose, insulin resistance, leptin resistance, dyslipidemia and increased expression of I-FABP in the small intestine." (PMID 37237272, 2023). "The following keywords were used: “metabolic syndrome”, “melatonin”, “women”, “ghrelin”, and “leptin”." (PMID 37371675, 2023). "Given the published association between metabolic syndrome and RV dysfunction in PAH, we sought to determine the association between leptin and RV dysfunction." (PMID 37869164, 2023). "Apelin-13 was reported to improve glucose metabolism, dyslipidemia, insulin sensitivity, and decrease leptin levels in an HFD-induced T2DM model." (PMID 37424869, 2023). "Leptin is thought to be an important factor linking metabolic syndrome and cardiovascular disorders." (PMID 37869164, 2023). "Serum adiponectin/leptin ratio (A/L ratio) is a surrogate marker of IS that correlates well with signs of metabolic syndrome in childhood and adolescence." (PMID 36676079, 2023). "A previous study found increased body weight, increased plasma insulin and leptin levels and decreased insulin sensitivity after four-week corticosterone administration via drinking water, proposing a potential animal model of the metabolic syndrome." (PMID 36756053, 2023). "Leptin It is also found to be over-expressed in patients with metabolic syndrome synergistically with overexpression in BDNF and NGF- β." (PMID 36248655, 2022). "HF diet exposure in utero increased the prevalence of metabolic syndromes-like phenomena through histone methylation of adipocytokine, adiponectin, and leptin gene expression in the adipose tissue of offspring mice." (PMID 35745181, 2022). "It was reported that adiponectin to leptin ratio, being known as a marker of dysfunctional adipose tissue, was significantly reduced in metabolic syndrome patients." (PMID 35042855, 2022). "Herein, J-12 improved dyslipidemia, insulin and leptin resistance, activated adiponectin, and reduced pancreatic and hepatic tissue damage in rats with HIP." (PMID 36615827, 2022). "Increased leptin levels also positively affect the incidence of metabolic syndrome and cardiovascular disease." (PMID 36431836, 2022). "Dyslipidemia, perirenal and epididymal fat accumulation, hepatic steatosis, and increases in triglyceride and plasma leptin levels were observed in the LC group but were attenuated by FO supplementation." (PMID 35565762, 2022). "Pro-inflammatory adipokines (leptin and resistin) and pro-inflammatory cytokines (IL-1 β) were considered as potential metabolic syndrome serum markers." (PMID 35779187, 2022). "Experimental studies have demonstrated that fructose is able to induce leptin resistance and bring about metabolic syndrome in rats." (PMID 35643436, 2022). "Simvastatin can effectively improve airway inflammation and remodeling by regulating dyslipidemia and decreasing leptin levels." (PMID 36051916, 2022). "The serum DPP-4 levels were positively correlated with adipocyte size and metabolic-syndrome indices, such as BMI, insulin, and leptin, and negatively correlated with age and adiponectin levels." (PMID 35893426, 2022). "This is in line with earlier observations showing that in persons with the metabolic syndrome, 6-fold higher plasma leptin concentrations have been measured compared to controls." (PMID 35745267, 2022). "The leptin-deficient ob/ob mice and insulin-deficient T1DM mice were established to confirm that insulin and leptin are essential for APF anti-metabolic syndromes by regulating adipoinsular axis." (PMID 36046814, 2022). "After adjusting for age, sex, smoking status, drinking status, BMI, uric acid levels, HTN, DM, and dyslipidemia, serum leptin levels and eGFR levels were still negatively correlated, with a regression coefficient of -0.14 and p value <0.001." (PMID 36619557, 2022).
metabolic syndrome (continued). "In our study, we found abnormalities in the concentrations of leptin and ghrelin in schizophrenia patients with metabolic syndrome." (PMID 36294794, 2022). "Along which pathway leptin and ghrelin contribute to the development of metabolic syndrome in people with schizophrenia is uncertain." (PMID 36294794, 2022). "At metabolic and physiological levels, CGL subjects present dyslipidemia, hyperinsulinemia, IR, DM, low levels of leptin and adiponectin, decreased levels of high-density lipoprotein cholesterol (HDL-c), hepatosplenomegaly, and hypertrophic cardiomyopathy." (PMID 36354755, 2022). "Previous studies have pointed out that plasma leptin levels were increased in schizophrenia patients and that leptin was closely related to weight gain, abnormal glucose metabolism and dyslipidemia in patients." (PMID 36090349, 2022). "A metabolic syndrome biomarker, the adiponectin/leptin ratio, was found to be lower in the BCRL group than in the non-BCRL group (median: 0.28 vs. 0.41, p < 0.05)." (PMID 36232660, 2022). "Previous studies have separately addressed the distinct roles of NRF2 and leptin signaling on energy homeostasis and metabolic syndrome." (PMID 35323110, 2022). "The concept of MHO describes an expansion of adipose tissue that is the result of an increased storage capacity, attenuated inflammation of the adipose tissue, elevated secretion of adiponectin and leptin and dyslipidemia." (PMID 35626717, 2022). "Individuals with severe coronary artery disease, metabolic syndrome or abdominal obesity display decreased adiponectin and increased leptin plasma levels." (PMID 35057479, 2022). "Adiponectin, leptin and plasminogen activator inhibitor 1 can be used as biomarkers to predict metabolic syndrome among adolescents." (PMID 36339176, 2022). "Increased levels of sDPP4 have also been detected in metabolic syndrome, where sDPP4 positively correlated with various parameters such as body mass index, adipocyte surface, and leptin and insulin levels." (PMID 36009573, 2022). "The impact of BPA on dyslipidemia is because of disruption of several hormones such as adiponectin and leptin regulating the energy consumption, alteration of several metabolic functions and destruction of endogenous hormones." (PMID 34290970, 2021). "Others have reported that leptin and hsCRP are elevated in individuals with CVD risk and metabolic syndrome." (PMID 33125159, 2021). "Earlier studies have demonstrated that circulating leptin levels were high in obese individuals and in patients with metabolic syndrome." (PMID 34368053, 2021). "In contrast to leptin, the concentration of adiponectin decreases as the number of metabolic syndrome components increases." (PMID 33842335, 2021). "Studies have concluded that leptin and adiponectin receptors seem to be the most promising molecular targets for the treatment of metabolic syndrome-related cancers." (PMID 33842335, 2021). "Peripheral leptin resistance is linked to the development of NAFLD and metabolic syndrome in children." (PMID 34357000, 2021). "Sitagliptin effectively improved diet-induced metabolic syndrome and fatty liver via regulation of adipose tissue inflammation and hepatic adiponectin/ leptin levels." (PMID 34446063, 2021). "Further, the levels of key biomarkers of metabolic syndrome, leptin, resistin, adiponectin, PAI-1, and ghrelin were measured." (PMID 34579036, 2021). "Previously reported, the abundance of Parabacteroides was significantly decreased in obese subjects with metabolic syndrome, and nonalcoholic fatty liver disease, and negatively correlated with weight gain and leptin plasma levels." (PMID 33639944, 2021). "High plasma leptin level is related to the development of essential hypertension, hyperinsulinemia and dyslipidemia." (PMID 34746061, 2021).
metabolic syndrome (continued). "It has been shown that high palmitate levels are present in the CSF of obese patients and patients with metabolic syndrome, and palmitate is able to induce a neuroinflammatory response with hypothalamic insulin and leptin resistance." (PMID 33946318, 2021). "Several adipokines, including Leptin, fetuin-A, and adiponectin, are associated with risk of obesity, type 2 diabetes (T2DM), metabolic syndrome (MetS), and CVD." (PMID 34696714, 2021). "Weight status, body fat percentage, leptin levels, metabolic screening for dyslipidemia, glucose intolerance, and fatty liver should be investigated in these cohorts with standardized methods." (PMID 34448070, 2021). "Previous clinical studies have also shown that fenofibrate affects the level of leptin in patients with dyslipidemia and hypertriglyceridemia and improves insulin sensitivity." (PMID 34988225, 2021). "In metabolic syndrome, respectively, in diabetic patients, a lower ghrelin/BMI ratio and a higher leptin/ghrelin/BMI ratio were also found." (PMID 34829886, 2021). "We aimed to explore the prevalence of maternal dyslipidemia, its influencing factors and effects on the physical development of fetuses and infants, as well as the role of leptin in this process." (PMID 34684402, 2021). "Now with the present study findings in hand, further detailed studies of the nature of the involvement of leptin resistance in the expression of the metabolic syndrome induced by SCN-dopaminergic neuronal lesion are warranted." (PMID 33485386, 2021). "These cytokines, especially TNF-α and leptin, seem to aggravate hypertension, which, together with visceral obesity, dyslipidemia, and hyperglycemia, configure the metabolic syndrome scenario." (PMID 33807959, 2021). "Especially, a high leptin–adiponectin ratio appears to be a suitable biomarker for metabolic syndrome." (PMID 33066473, 2020). "In contrast, CME ameliorated HFD increased body weight, hyperglycemia, dyslipidemia, ketonemia, hepatic tissues lipid peroxidation, restored hepatic tissue architecture and enhanced protein expression of leptin, adiponectin and UCP1 and activity of hepatic GR." (PMID 32197395, 2020). "Obese and metabolic syndrome patients have both insulin and leptin resistance leading to appetite stimulation further exacerbating rises in insulin and leptin levels." (PMID 32708430, 2020). "It is worth noting that the relationship between serum leptin and metabolic syndrome is very prominent in men and postmenopausal women, but weak in young women." (PMID 33114326, 2020). "On the other hand, leptin has been long identified as a pro-inflammatory metabolite that exacerbates inflammation in conditions of metabolic syndrome." (PMID 32375340, 2020). "The relationship of omentin to metabolic syndrome, age, serum leptin, sex steroids, SHBG was also investigated." (PMID 32326011, 2020). "The ratio of circulating APN/leptin is emerging as a marker for metabolic syndrome, which includes hypertension, and our results indicate that VSMCs can now be viewed as contributors to this change in ratio." (PMID 32566092, 2020). "Although the role of adiponectin and leptin in the etiology of metabolic syndrome (MetS) has been explored in various populations, limited knowledge is available on the prospective association of adiponectin and leptin with the risk of MetS development." (PMID 32397260, 2020). "In metabolic syndrome, levels of leptin are increased aggravating leptin resistance enhancing chronic inflammation." (PMID 33330597, 2020). "As expected, we observed significantly higher HOMA-I and leptin levels in PC patients with MS compared to the non-metabolic syndrome individuals with PC, the same observations were made for patients with BPH." (PMID 32326011, 2020). "Recent reports suggested that leptin and adiponectin play important roles in the development of the metabolic syndrome." (PMID 32559253, 2020).
metabolic syndrome (continued). "The role of ceramides in metabolic syndrome will be discussed further in later sections examining the interaction of ceramides with adiponectin and leptin, respectively." (PMID 33133017, 2020). "Leptin correlates with metabolic syndrome features and inflammation in patients with moderate-to-severe psoriasis." (PMID 33643281, 2020). "Some new shreds of evidence have shown that leptin is positively related to dyslipidemia in contrast to adiponectin, which is negatively related to dyslipidemia." (PMID 32430022, 2020). "Collectively, our data demonstrate that LEPRs in RIP-Cre25Mgn neurons significantly contribute to glucose-lowering effects of leptin in an insulin-independent manner by improving dyslipidemia." (PMID 33071988, 2020). "This study indicated that HFD increased food intake and body weight gain and induced dyslipidemia and hyperglycemia in rats through reducing leptin, adiponectin and UCP1 protein production." (PMID 32197395, 2020). "This also implicates abnormal serum leptin in inducing impairment in CNS leptin receptor-dependent mechanisms and contributing to metabolic syndrome development." (PMID 33114326, 2020). "This study indicated that CME ameliorated HFD induced hyperglycemia and dyslipidemia through normalization of HFD reduced leptin, adiponectin and UCP1 proteins production and antioxidant activity." (PMID 32197395, 2020). "A lower adiponectin–leptin ratio is considered a predictive marker of adipose tissue dysfunction, chronic low-grade inflammation, and metabolic syndrome." (PMID 33036196, 2020). "Apart from protein and omega-3 PUFA, taurine is reported to promote insulin release in pancreatic β-cells, reduce insulin and leptin resistances, and thus ameliorate hyperglycemia and dyslipidemia." (PMID 33322303, 2020). "As the leptin/adiponectin ratio serves as a new atherosclerotic indicator, it is a sensitive index in estimating obesity and dyslipidemia." (PMID 32430022, 2020). "Maternal HFD also programmed the development of metabolic syndrome, characterized by increases in fasting plasma insulin, glucose, triglyceride and leptin levels, as well as HOMA index." (PMID 32446297, 2020). "Although both adiponectin and leptin levels have the potential to be biomarkers for predicting metabolic syndrome, recent studies have suggested leptin/adiponectin ratio (L/A ratio) as a stronger candidate as compared with adiponectin and leptin alone." (PMID 33551872, 2020). "ALiOS feeding resulted in metabolic syndrome, as indicated by an increase in serum insulin and leptin levels and a drop of adiponectin levels." (PMID 33202693, 2020). "On the other hand, some adverse effects of leptin have such as direct contact with the components of metabolic syndrome and impaired fibrinolysis have been reported." (PMID 33148166, 2020). "Underexpression of the adiponectin gene (ADIPOQ) and simultaneous upregulation of leptin (LEP) were detected in the analysis of the transcriptome from the adipocytes of patients with metabolic syndrome after coronary artery bypass grafting." (PMID 32121175, 2020). "Modified lingguizhugan decoction improves liver fat accumulation and IR in rats with metabolic syndrome by inhibiting abnormal increases in leptin and PKB in the liver." (PMID 31258478, 2019). "Sleep restriction lowers appetite suppressing hormone (leptin) and increases appetite promoting hormone (ghrelin), leading to high dyslipidemia including low HDL and high LDL36." (PMID 31740698, 2019). "Hypertriglyceridemia (one of the dyslipidemias) will result in elevated peripheral leptin levels, which prevent the entry of leptin to the brain, thus harming brain development, and consequently lowers cognitive performance." (PMID 31196019, 2019). "Horses with metabolic syndrome showed marked adipocyte hypertrophy and increased expression of adipokines (leptin) and inflammatory cytokines (TNFα,IL1β and CCL2) in both adipose tissue depots compared to healthy horses." (PMID 30866087, 2019).